CCND1 (cyclin D1)
Diseases named in the same sentence as CCND1 in open-access papers (continued):
Sharing a sentence is not in itself a finding about the gene and the disease.
lymphoma (continued). "A few pieces of research have been reported on the expression of cyclin D1 in triple-hit lymphoma, renaming it quadruple-hit lymphoma." (PMID 36312606, 2022). "eFT226 also caused a G1 cell cycle arrest in lymphoma cell lines due to the inhibition of translation of MYC, CDK4 and cyclin D1, which led to anti-tumor activity in vivo." (PMID 34398253, 2021). "A gene mutation that resulted in a premature polyadenylation signal in CCND1 shortened its 3′-UTR and increased the risk of lymphoma." (PMID 34007269, 2021). "The pathophysiology responsible for the majority of lymphomas involves overexpression of cyclin D1 and even higher in MCL." (PMID 33655156, 2019). "c-Myc and cyclin D1, two NF-κB gene targets essential for lymphoma cell proliferation and survival, were also dramatically decreased by DHI treatment." (PMID 28906487, 2017). "These early lesions occurred 2–86 months prior to the diagnosis of classic lymphoma, which were characterized by small groups of cyclin D1-positive lymphocytes in the mantle zone of lymph node or extra nodal tissue." (PMID 29246179, 2017). "The concurrent presence of a MYC and CCND1 rearrangement is rare, accounting for approximately 10% of the patients with double hit and triple hit lymphomas in the Mitelman database." (PMID 26517511, 2015). "Aberrant cyclin D1 expression seems to promote proliferation in other types of lymphoma, while a growth promoting CCND1/Trop2 fusion product has also been described in these tumors." (PMID 26000093, 2015). "Our findings is consistent with the results from lymphoma and esophageal cancers, supporting the notion that the alternative splicing of CCND1 gene also depends on cell origin." (PMID 25851350, 2015). "In invasive breast cancer, protein expression of BCL-6 was observed to be associated with cyclin D1 and hypoxia-inducible factor-1-alpha (HIF-1-alpha), first suggesting that BCL-6 oncogene activation plays a role in cancers other than lymphomas." (PMID 25477702, 2014). "For example, c-Myc, cyclin D1 and Mcl-1 were quickly down-regulated in lymphoma cells when cap-dependent translation was blocked." (PMID 23402580, 2013). "PRMT5 has been shown to be over-expressed in BL cell lines; to suppress the retinoblastoma family of tumour suppressors in leukaemia and lymphoma cells; and to mediate CCND1-dependent neoplastic growth in a mouse lymphoma model." (PMID 25436604, 2012). "FISH analysis with BAP for CCND1 demonstrated a break only in those areas where cyclin D1 was positive indicating that the translocation was indeed a secondary genetic event in the evolution of this lymphoma." (PMID 37555980, 2023). "However, to date, very limited data are available at the international level regarding cyclin D1 expression in triple-hit lymphoma to label it as quadruple-hit lymphoma." (PMID 36312606, 2022). "Up-regulation of cyclin D1 increases proliferation of leukemia and lymphoma cells, and may upregulate anti-apoptotic proteins, leading to a block in apoptosis." (PMID 26262635, 2015).
lymphoma (continued). "By 28 hrs post-drug delivery, there was a reduction in the amount of Mcl-1, Cyclin D1, and c-Myc protein levels in Pten+/−Eμ-Myc lymphomas relative to vehicle-treated controls (compare lanes 2–6 to 1) whereas the levels of β-actin or Bcl-2 did not appreciably change over this time period." (PMID 19412536, 2009). "While mutational profile is not necessarily specific to a particular type of lymphoma, mutations in CCND1, RB1, CTNNA2, NSD2, and to a lesser degree, certain types of mutations in ATM, are predominantly seen in MCL in comparison to other common mature B- and T-cell lymphomas." (PMID 34888236, 2021). "Indeed, since mantle cell lymphoma overexpress cyclin D1, a key protein involved in the G1/S transition phase and regulated by mTOR signalling, this lymphoma was the first hematologic disease in which the therapeutic efficiency of mTOR inhibitors was investigated." (PMID 30704144, 2019). "In this context, lncRNAs such as GAS5, MEG3, CCND1, MORT, and LincRNA-p21 are downregulated in breast, lung, prostate, and renal cancers, as well as in leukaemia and lymphomas." (PMID 41597397, 2026). "In several lymphomas, PRMT5 acts synergistically with key tumorigenic drivers, including cyclin D1, c-Myc, and NOTCH1, to regulate the lymphomagenic process." (PMID 41154773, 2025). "In lymphoma cells, deceased PRMT5 represses TP53K372 methylation, cyclin D1 transcriptional activation, and BCL3 production and promotes NF-κB p52–HDAC1 repressor complexes to the cyclin D1 promoter." (PMID 38257273, 2024). "Our analyses revealed higher BACH1 expression in MCL than other lymphoma subtypes, and a significant positive correlation between BACH1 and CCND1 was also discovered in patients with MCL, implying a potential oncogenic role of BACH1." (PMID 34039348, 2021). "However, ricolinostat did not cause downregulation of cyclin D1 in lymphoma cell lines, and it remains to be determined whether ricolinostat or other HDAC6 selective inhibitors being developed are effective at downregulating MYC and FGFR3 or other FGFRs." (PMID 29423038, 2018). "BL is a typical highly proliferating and malignant MYC-driven lymphoma, while MCL is a CCND1-positive lymphoma with a heterogeneous clinical behaviour." (PMID 30038718, 2018). "B-PLL is in fact a heterogenous disease and those cases that are positive for cyclin D1 and carry the t(11:14) translocation are in the current WHO classification of malignant lymphomas considered to be leukemic forms of MCL." (PMID 19134178, 2009). "However, other lymphoma markers like CD3, cyclin D1, cytokeratin, epithelial membrane antigen (EMA), vimentin, B-cell lymphoma 2 (BCL2), CD117, CD34, desmin, and smooth muscle actin (SMA) were positive only in 1 case each." (PMID 36511607, 2023). "However, they have largely focused on the expression of lymphoma surface antigens (CD20), disease markers (PAX5, cyclin D1) and proliferation rate by Ki-678." (PMID 35488033, 2022). "Though cyclin D1 is one of the most persistent nuclear markers for MCL, it can be absent in a subset of lymphoma known as cyclin D1-negative MCL." (PMID 34430143, 2021). "While some of the affected genes such as ATM, CCND1, and KMT2D are known to be mutated in MCL, a large subset has not been reported as mutated before in this lymphoma but mutated in other types of lymphoma, as detailed in the Results section." (PMID 31334109, 2019). "Overexpression of cyclin D1 is a hallmark of MCL, whereas cyclins D2 or D3 are not as specific to certain lymphomas as cyclin D1." (PMID 30755239, 2019). "SOX11 has also recently emerged as a tumor marker for MCL, particularly in cyclin D1-negative MCLs and to distinguish between MCLs and other cyclin D1-positive lymphomas." (PMID 31714947, 2019). "However, Cyclin D1 protein has been shown to be significantly expressed in a number of EBV positive LCLs or EBV positive SCID mice lymphomas." (PMID 21347341, 2011).
lymphoma (continued). "However, a number of studies showed noticeable changes in Cyclin D1 protein levels in both EBV positive LCLs and EBV positive SCID mice lymphomas." (PMID 21347341, 2011). "Immunohistochemical analysis showed strong diffuse positivity for CD99, alongside vimentin, BCL2, Cyclin D1, and C-Kit expression, while markers such as CK7, CK20, S100, and CD34 were negative, effectively ruling out differential diagnoses such as rhabdomyosarcoma, lymphoma, and other SRCTs." (PMID 41466962, 2025). "Immunohistochemistry of intrathoracic biopsy revealed that the tumor cells were positive for CD20, CD30, c-Myc, BCL-2, Mum-1, and PD-L1 but negative for CD3, CD5, CD10, BCL-6, PD-1, and cyclin D1, conforming to the pathological diagnosis of diffuse large B-cell lymphoma (DLBCL))." (PMID 33564306, 2021). "A few cases of Cyclin D1-negative lymphoma with morphologic, pathologic, clinical, and molecular features typical of MCL have also been reported; these typically lack evidence of chromosomal translocations or genomic amplifications but possess high levels of cyclin D2 or D3." (PMID 27119356, 2016). "Interestingly, the Emu-T286A CCND1 transgenic mice, which constitutively expressed nuclear mutant CCND1, developed lymphoma without introducing a second genetic hit." (PMID 27713153, 2016). "But cyclin D1 is not enough to develop spontaneous lymphomas in transgenic mice." (PMID 26517511, 2015). "In addition, we showed molecular alteration never described in the literature for this type of lymphoma which affects cyclin D1 expression through gene gain of function." (PMID 22770229, 2012). "However, lymphoma cells were positive for cyclin D1 and negative for SOX11 (not shown)." (PMID 39691246, 2024). "As the neoplastic cells were negative for CD3, CD23, cyclin D1, Tdt, SOX11, and MUM1, the mantle and marginal zone lymphomas that can occur at this site were ruled out." (PMID 40027040, 2025). "Immunohistochemistry stains of lymphoma cells were positive for CD20, CD79a, CD10, MUM1, BCL6, C-MYC, and negative for BCL2, cyclin D1, CD5, and CD3." (PMID 36120205, 2022). "In our patient, immunohistochemical analysis for lymphoma revealed positive immunostaining for CD79a, CD20, and cyclin D1, but there was no immunostaining for CD10 or CD23." (PMID 28705174, 2017). "An incisional biopsy from the left lacrimal gland revealed diffuse and intense CD20, CD5, and bcl-2 positivity with negative cyclin D1 and CD23 which supported lymphoma." (PMID 27738539, 2016). "FISH analyses using BAC clones covering lymphoma breakpoints (BCL2, BCL6, BCL11A, CCND1, CCND3, IG-H/K/L, JAK2, LMO2, MYC, PAX5, REL) all tested normal, excluding rearrangements at these loci." (PMID 26599546, 2015). "“Quadruple-hit” lymphomas, while not a defined entity in either the WHO or ICC classification schema, have been characterized by the concurrent presence of MYC, BCL2, BCL6, and CCND1 rearrangements, and are extremely rare with an apparent dismal prognosis." (PMID 38914869, 2024). "However, the lymphoma B-cells are positive for CD5, and CD23 but lack CD10, CD21, and cyclin D1, and this confirms the diagnosis and excludes MALT lymphoma." (PMID 37958219, 2023). "During lymphomagenesis, cyclin D1 requires cooperation of alterations in other genes, as supported by studies on transgenic mice, which showed that mice solely carrying CCND1 rearrangement did not develop spontaneous lymphomas." (PMID 34888236, 2021).
liver cancer (114 papers, 2008 to 2025). An epithelial or non-epithelial malignant neoplasm that arises from the liver. "It has been reported that CCND1 amplification and high CCND1 expression can be independent risk factors for liver cancer." (PMID 40852585, 2025). "Crucially, the insulin-dependent induction of cyclin D1 has been shown to be a risk factor for liver cancer in the context of obesity and/or type 2 diabetes." (PMID 36091143, 2022). "It has been demonstrated that cyclin D1 is overexpressed in the liver in response to hyperinsulinemia, a risk factor for the development of liver cancer." (PMID 36091143, 2022). "EZH2 c.1544A>G and CCND1 c.839A>T were found in five liver cancer patients with the highest mutation frequency." (PMID 34604069, 2021). "Another study suggested that FXR deficiency initiates liver cancer in mice; however, excess bile acids are essential for the progression of tumor via initiating cyclin D1 and suppressing cell cycle inhibitors." (PMID 35006466, 2021). "The increased level of cyclin D1/cyclin E in liver cancer leading to the decreased BTG2 expression causes the increase of tumor grade." (PMID 34217312, 2021). "Additionally, Cyclin D1 is known to play critical roles in various cellular processes associated with liver cancer." (PMID 38722372, 2024). "CD55 and CCND1 are reportedly associated with cancer progression, as demonstrated in liver cancer." (PMID 37745301, 2023). "Besides, the loss of FXR in obese diabetic mice develops liver cancer through increased cell division cycle 25B (Cdc25b), Cyclin D1, and forkhead box protein M1 (FoxM1)." (PMID 35006466, 2021). "In addition, the high expression of the CCND1 gene, which encodes cyclin D1 protein has been verified in vitro and in vivo to cause appreciable elevation in liver cancer stem cell differentiation by intensifying cell autophagy." (PMID 33292207, 2020). "Thus, liver cancer cells appear to hijack Smad2/3 and Smad4 for CSCs, and this process is closely associated with oncogene cyclin D1 regulation." (PMID 28415588, 2017). "The mutation of other genes, including β-catenin, SMAD2, SMAD4, p16 INK4a, and Cyclin D1, may also be implicated in liver cancer." (PMID 22091434, 2011). "ZNF384 was shown to act as a direct transcriptional regulator of Cyclin D1, binding to its promoter region, in liver cancer." (PMID 40405535, 2025). "Studies show that inhibiting autophagy by silencing CCND1 in turn inhibits the differentiation of liver cancer." (PMID 38397131, 2024). "miR-193a-5p has been shown to induce G1 phase cell cycle arrest by targeting NUSAP1 in liver cancer cells, which in turn downregulates Cyclin E1, Cyclin D1, Cyclin B1, and Cyclin A2 and induces p21 expression." (PMID 39273339, 2024). "ZBTB7B bound to the promoters of known ZBTB7B targets genes, e.g., Irs1, as well as genes important in liver cancer, including Jun, Akt1, Ccnd1, and Mki67." (PMID 38225233, 2024). "Investigations by Hongying Zhang and team found that CCND1 suppression, achieved by gene silencing, impedes the differentiation of hepatic cancer stem cells by inhibiting autophagy." (PMID 38953023, 2024). "Our prior studies found that cyclin D1 regulates the expression of a broad range of metabolic enzymes at the mRNA and/or protein expression level in liver, hepatocytes, and liver cancer cell lines." (PMID 38152849, 2023).
liver cancer (continued). "Cancer literatures proved that miR-22-3p targets SP1, inhibits the expression of downstream genes CCND1 and BCL2, thereby inhibiting the growth of liver cancer cells, and the low expression of miR-22-3p is associated with metastatic liver cancer." (PMID 35011220, 2022). "Suppression of cyclin D1 in Huh7 and HepG2 human liver cancer cell lines by anti-tumor agents was earlier suggested to block cyclin D1 turnover." (PMID 34298825, 2021). "An increase in Hint1 expression by Taraxasterol inhibits the growth of liver cancer cells and regulates Bax, Bcl2, and cyclin D1 expression in human liver cancer." (PMID 33671384, 2021). "Knockdown of CNPY2 in Huh7 and HepG2 human liver cancer cells resulted in significant suppression of cell survival and invasive potential, inhibition of cyclin D1, induction of p21Waf1/Cip1 and suppression of the apoptosis inhibitor Bcl2." (PMID 34298825, 2021). "Knocking out the FRAT1 gene downregulates β-catenin, cyclin D1, and c-myc expression in liver cancer cells and inhibits tumor cell proliferation by regulating the Wnt/β-catenin signaling pathway." (PMID 32201513, 2020). "Cell cycle abnormality evidently has a key role during the process of liver cancer, and cyclin D1 degradation has been reported to inhibit HCC occurrence." (PMID 33193629, 2020). "We found that HMGCS2 controls the proliferation and migration abilities of liver cancer cells by regulating the apoptosis, c-Myc/cyclin D1, and EMT signaling pathways and acts in a ketone-dependent manner." (PMID 32635582, 2020). "On the other hand, overexpression of cyclin-dependent kinases (CDK6 and Cyclin D1) was observed in untreated breast, lung, and liver cancer cells in the present study, corroborating previous reports." (PMID 31783627, 2019). "Overall, Scrib inhibits liver cancer cell proliferation by suppressing the expression of three oncogenes, Yap1, c-Myc and cyclin D1, thereby functioning as a tumor suppressor in liver cancer." (PMID 28460446, 2017). "In this study, we demonstrated the biological function of cyclin D1 in liver cancer spherogenesis, which consists of enhancing liver CSC population and the expression of stemness transcription factors, which increases chemotherapy resistance." (PMID 28415588, 2017). "Cyclin D1 promotes passage through phase G1 of the cell cycle and is overexpressed in liver cancer; overexpression of cyclin D1 appears to promote cancer cell invasion." (PMID 27153056, 2016). "Several genes previously implicated in liver cancer were discovered by our screening, including KLB, FGF19, FNDC3 and CCND1." (PMID 23776502, 2013). "Ectopic expression of either FZC18 (35 kD) or its 50 kD precursor inhibited Wnt/β−catenin signaling in colorectal and liver cancer cell lines, thus downregulating major cell cycle checkpoint gatekeepers cyclin D1 and c-myc and reducing tumor cell growth." (PMID 18382662, 2008). "Moreover, HULC promotes autophagy through the miR-675/PKM2 axis, leading to upregulation of Cyclin D1 and accelerated proliferation of liver cancer stem cells." (PMID 40909946, 2025). "APS (both 100 and 200 mg/L) can suppress the activity of the Wnt/β-catenin pathway by downregulating the mRNA and protein expression of β-catenin, C-myc, and cyclin D1, as well as by inhibiting the antiapoptotic gene Bcl-2, thereby inducing apoptosis in HepG2 liver cancer cells." (PMID 40649307, 2025). "In HCC, autophagy could promote the cancer development, for example, CCND1 silencing inhibited liver cancer stem cell differentiation by suppressing autophagy." (PMID 36618969, 2022). "Importantly, inactivation of cyclin D1 in the liver drastically reduced the incidence of liver cancer in obese/diabetic mice." (PMID 36091143, 2022). "Ccnd1 silencing suppresses liver cancer stem cells (LCSCs) differentiation." (PMID 36279394, 2022). "MCM7 promotes liver cancer progression through cyclin D1-dependent signaling." (PMID 33952716, 2021).